RN7SL847P (RNA, 7SL, cytoplasmic 847, pseudogene)
Gene: Miscellaneous RNA gene on chromosome 10 (33,034,655 to 33,034,924, reverse strand). Ensembl gene ENSG00000265319.
Homologues: Orthologues: chimpanzee Metazoa_SRP (99% identical), macaque Metazoa_SRP (40% identical). Paralogues in human: RN7SL155P (66% identical), RN7SL32P (63% identical), Metazoa_SRP (63% identical), Metazoa_SRP (61% identical), RN7SL602P (61% identical), RN7SL353P (60% identical), RN7SL850P (60% identical), Metazoa_SRP (60% identical), RN7SL198P (60% identical), Metazoa_SRP (59% identical), RN7SL121P (59% identical), RN7SL154P (59% identical), and 699 more.